NKX2-1 (NK2 homeobox 1)
Diseases named in the same sentence as NKX2-1 in open-access papers (continued):
Sharing a sentence is not in itself a finding about the gene and the disease.
lung disease (13 papers, 2017 to 2025). "HCQ remains controversial in the treatment of lung disease because of the presence of NKX2-1 pathogenic variants." (PMID 41181172, 2025). "Clinical diversity: This study reveals a wide spectrum of respiratory conditions associated with NKX2-1-RD, encompassing neonatal respiratory distress to various severe lung diseases, highlighting the heterogeneous nature of this clinical entity." (PMID 40395234, 2025). "Respiratory manifestations in NKX2-1-RD range from neonatal respiratory distress to severe lung diseases, constituting a leading cause of mortality." (PMID 40395234, 2025). "The wide impact of the pathogenic NKX2-1 variants on human development and neurological, endocrinological, and pulmonary diseases demonstrates the ongoing scientific challenges and issues." (PMID 38916623, 2024). "Furthermore, more randomized or controlled studies with more clinical phenotypes and more combination treatment options are required to evaluate the effects of HCQ treatment on lung disease caused by NKX2-1 pathogenic variants." (PMID 41181172, 2025). "In this report, we show that the c.464‐9C>A variant in the NKX2‐1 gene can be associated with life‐threatening infantile lung disease, and that treatment with hydroxychloroquine, azithromycin, and prednisolone might be helpful in such cases." (PMID 28588801, 2017). "Hence, the NKX2-1 mutation may have affected SP-C function and caused recurrent pulmonary infection or other lung diseases." (PMID 32195974, 2020). "Regarding clinical alterations related to NKX2-1-RD, 57.8% of patients reported neurological, thyroid, and lung disease (a complete triad)." (PMID 38990976, 2024). "Given the absence of previous reports in the literature or databases, this case broadens the mutational landscape of NKX2-1 and reinforces its link to isolated choreic phenotypes with thyroid involvement but no pulmonary disease." (PMID 41423511, 2025). "The authors demonstrated that the coactivator TAZ/WWTR1 (transcriptional coactivator with PDZ-binding motif/WW domain-containing transcription regulator protein was able to restore NKX2-1 transactivation suggesting a potential role of TAZ in the development of the lung disease." (PMID 36733766, 2022). "In this report we describe a family of two siblings, and their mother with a NKX2‐1 mutation that has not previously been associated with lung disease." (PMID 28588801, 2017).
melanoma (13 papers, 2008 to 2025). A malignant, usually aggressive tumor composed of atypical, neoplastic melanocytes. "Conversely, ectopic expression of NKX2-1 in melanoma cells lead to an increase in ABI3 expression." (PMID 27036019, 2016). "In melanoma cells, even though the CpG sites at this specific region were hypomethylated, ABI3 could not be detected, most likely because NKX2-1 was absent in these cells." (PMID 27036019, 2016).
benign hereditary chorea (11 papers, 2014 to 2025). "In conclusion, our case adds to the growing body of evidence supporting the association between NKX2-1 mutations and benign hereditary chorea." (PMID 41423511, 2025). "Mutations in NKX2–1 cause benign hereditary chorea and have recently been associated with autism." (PMID 32912160, 2020). "Mutations in TITF1/NKX2-1 are the most common cause of benign hereditary chorea (BHC)." (PMID 32832197, 2020). "NKX2-1-related disorders (NKX2-1-RD, OMIM#610978), also known as Benign Hereditary Chorea (BHC), is a rare condition that affects the development and function of the lungs, thyroid, and brain." (PMID 38990976, 2024). "Investigators from the Institute of Neurology, London, UK, and centers in Italy, Germany, and Greece, studied 18 unrelated cases of benign hereditary chorea BHC (7 familial, 11 sporadic) who were negative for NKX2-1 mutations." (PMID 26933606, 2015).
Dystonia (11 papers, 2013 to 2025). An abnormally increased muscular tone that causes fixed abnormal postures. "NKX2-1 variants display childhood-onset chorea, which sometimes is associated with dystonia and ataxia, helping to differentiate these conditions." (PMID 40724495, 2025). "When addressing a patient presenting with a combination of dystonia and chorea, it is worth keeping in mind the NKX2-1 gene." (PMID 40724495, 2025). "This was the first DBS treatment of a NKX2-1-related dystonia." (PMID 38916623, 2024). "Multiple CNVs affecting SPG7 (n = 4), CACNA1A (n = 3), SGCE (n = 3), NKX2-1 (n = 2) and SPAST (n = 2) were detected in individuals with episodic ataxia, dystonia, or spastic paraplegia, respectively." (PMID 36781956, 2023).
thyroid dysgenesis (10 papers, 2014 to 2025). "The possible causes of thyroid dysgenesis include the impact of maternal antithyroid immunoglobulins, genetic mutations, and genes of transcription factors, such as TITF1/NKX2–1, PAX8, FOXE1, and HHEX." (PMID 34713843, 2021). "Notably, eight mutations in four genes (FOXE1, NKX2-1, PAX8 and HHEX) that lead to thyroid dysgenesis were identified in eight probands." (PMID 29650690, 2018). "Mutations in the genes for TSH receptor, NKX2-1 (thyroid transcription factor 1), thyroid transcription factor 2, and paired box transcription factor 8 (PAX8) have been identified in some patients with various forms of thyroid dysgenesis." (PMID 28060725, 2017). "Cases of thyroid dysgenesis are usually sporadic, inherited genetic defects are only recognized in about 2% of all cases and result from transcription factor genes mutations (PAX8, NKX2-1/TITF1, NXK2-5, FOXE1/TITF-2)." (PMID 25908941, 2015).
diffuse large B-cell lymphoma (8 papers, 2013 to 2021). "Thus for example, NKX2-1 is ectopically expressed in diffuse large B-cell lymphoma (DLBCL), and the hematopoietic NKL homeobox genes NKX2-3 and NKX6-3 are overexpressed while MSX1 is downregulated in particular B-cell lymphomas." (PMID 30680064, 2018). "Here, using transcriptional microarray profiling and RQ-PCR we identified ectopic expression of NKL-family member NKX2-1, in a diffuse large B-cell lymphoma (DLBCL) cell line SU-DHL-5." (PMID 23637834, 2013). "In addition, NKX2-1 is aberrantly activated in diffuse large B-cell lymphoma (DLBCL) where it is deregulated by an altered chromatin configuration instead of a chromosomal rearrangement." (PMID 33921702, 2021). "Here, we introduce the NKL-code in normal hematopoiesis and focus on deregulated NKL homeobox genes in B-cell lymphoma, including HLX, MSX1 and NKX2-2 in Hodgkin lymphoma; HLX, NKX2-1 and NKX6-3 in diffuse large B-cell lymphoma; and NKX2-3 in splenic marginal zone lymphoma." (PMID 31779217, 2019). "However, in marginal-zone B-cell lymphoma NKX2-3 expression is aberrantly activated via chromosomal juxtaposition to the B-cell receptor gene, and in diffuse large B-cell lymphoma activation of NKX2-1 is mediated by chromatin alterations but not via direct chromosomal rearrangement." (PMID 28151996, 2017). "Furthermore, subsets of diffuse large B-cell lymphoma (DLBCL) and HL ectopically express the non-code members NKX2-1 and NKX2-2, respectively." (PMID 31141539, 2019).
interstitial lung disease (8 papers, 2017 to 2025). A diverse group of lung diseases that affect the lung parenchyma. "This study presents a case of brain–lung–thyroid syndrome caused by a pathogenic variant in the NKX2-1 gene, which is characterized by interstitial lung disease." (PMID 41181172, 2025). "This article describes a case of interstitial lung disease caused by a pathogenic variant in the NKX2-1 gene, whose oxygen demand decreased after treatment with hydroxychloroquine." (PMID 41181172, 2025). "The question whether interstitial lung disease in patients with pathogenic variants of NKX2-1 benefits from HCQ requires further research." (PMID 41181172, 2025). "Pathogenic variants in the genes that encode SP-B and SP-C (SFTPB and SFTPC) and genes that are involved in surfactant production (ABCA3 and NKX2-1) result in surfactant dysfunction disorders, one of the genetic causes of interstitial lung disease (ILD) (10, 19, –21)." (PMID 35121658, 2022).
Ataxia (6 papers, 2010 to 2025). Ataxia refers to impaired coordination of voluntary muscle movement. "In conclusion, patients with CH associated with respiratory pathology and choreoathetosis, ataxia or motor retardation should arouse suspicion of an altered TITF1/NKX2-1 gene." (PMID 22155464, 2011).
follicular thyroid cancer (6 papers, 2003 to 2021). "We confirmed that ABI3 was expressed in follicular carcinomas cells only when these specific CpG sites located at the promoter region of ABI3 (R1 region) were demethylated and NKX2-1 was present." (PMID 27036019, 2016).
lung squamous cell carcinoma (6 papers, 2018 to 2026). "This study was performed to determine the biological processes in which NKX2-1 is involved and thus its role in the development of lung squamous cell carcinoma (LUSC) toward improving the prognosis and treatment of LUSC." (PMID 38708353, 2024). "Previous studies have proven that inactivation of NKX2-1 would induce squamous differentiation, and CNV data supported this notion, i.e., lower frequencies in squamous cell lung carcinoma compared to LUAD." (PMID 39346064, 2024).
prostate carcinoma (6 papers, 2015 to 2025). A carcinoma that arises from epithelial cells of the prostate gland. "Although our RNA-Seq analysis identified NEPC as a cancer subtype in which NKX2–1 mutations are associated with increased PSPH mRNA expression, we did not further investigate this cancer subtype, due to the limited availability of prostate cancer models with neuroendocrine origin." (PMID 36932191, 2023). "NKX2-1 is highly expressed in NEPC and indispensable for NET of prostate cancer." (PMID 40691407, 2025).
Cognitive impairment (5 papers, 2016 to 2022). Abnormal cognition is characterized by deficits in thinking, reasoning, or remembering. "It would be interesting to determine whether restricted ablation of Nkx2-1 and Lhx6 in MGE neuroprogenitors, which cause seizure phenotypes and abnormal electroencephalographic activity, also leads to cognitive impairments similar to the ones observed here for Nkx2.1-CBPKO mice." (PMID 30334186, 2019). "In addition, we provide evidence for a causal link between NKX2-1 deficiency and memory deficits and suggest that cognitive impairment may constitute an integral phenotype of BHC and the broader spectrum of NKX2-1-related disorders." (PMID 28813670, 2017).
metastatic disease (5 papers, 2015 to 2025). "NKX2-1 is an organ-specific marker and is expressed in most lung primary adenocarcinomas, so its immunohistochemistry is commonly used to differentiate between primary lung tumors and metastatic neoplasm." (PMID 34290355, 2022). "NKX2-1 alterations were also enhanced in both BM and EM cohorts compared to patients without metastatic disease." (PMID 37591896, 2023).
Obesity (5 papers, 2016 to 2024). Accumulation of substantial excess body fat. "Consistently, it was recently reported that female mice with 26% loss of ERα neurons in the VMH (due to deletion of NKX2-1) develop profound obesity, associated with decreases in locomotor activity." (PMID 26988598, 2016).
asthma (4 papers, 2013 to 2024). "A comprehensive evaluation during gestational hypothyroidism diagnosis is vital, considering associated symptoms like motor developmental delay, abnormal movements, asthma, and recurrent respiratory infections, which could indicate underlying NKX2-1-RD." (PMID 38990976, 2024). "Moreover, reduced expression of airway epithelial FOXA2 and NKX2-1 expression was observed in patients with asthma." (PMID 24282527, 2013).
B-cell lymphoma (4 papers, 2013 to 2019). "Here, we investigate aberrant expression of NKL homeobox gene NKX2-1 in B-cell lymphoma cell line SU-DHL-5." (PMID 23637834, 2013). "Some of these identified genes have been previously shown to be deregulated in subsets of particular B-cell lymphomas, including HLX in HL, MSX1 in MCL, NKX2-1 in DLBCL, and NKX2-3 in SMZL, MALT lymphoma and DLBCL." (PMID 30308041, 2018). "Of note, NKL homeobox genes HLX, NKX2-1, NKX2-3, NKX6-3 and MSX1 are deregulated in B-cell lymphoma and show aberrant activity in T-ALL as well which might indicate similar oncogenic functions in both lineages of lymphoid malignancies." (PMID 29581848, 2018).
developmental delay (4 papers, 2014 to 2024). "NKX2-1-RD patients often have dysmorphic features, congenital anomalies, or developmental delay." (PMID 39466809, 2024).
mucinous lung adenocarcinoma (4 papers, 2018 to 2024). "The loss of function mutation of NKX2-1/CDKN2A can induce tumor development in patients with KRAS-G12D mutation in lung mucinous adenocarcinoma." (PMID 38817907, 2024). "Similarly, mice with KRAS mutations and NKX2-1 deletion develop lung tumors that resemble human mucinous lung adenocarcinomas." (PMID 30513627, 2018). "Knockdown of anti-mucous transcription factor, NKX2-1 (also known as TTF1) in KrasG12D induces mucinous adenocarcinoma of the lung in a murine model." (PMID 36860703, 2022).
pulmonary fibrosis (4 papers, 2017 to 2025). Chronic progressive interstitial lung disorder characterized by the replacement of the lung tissue by connective tissue, leading to progressive dyspnea, respiratory failure, or right heart failure. "Two are associated with pulmonary fibrosis (NKX2-1 and GATA6), another is involved in various cellular stress signaling pathways (ATF5)." (PMID 37206915, 2023). "Mutations in the gene encoding TTF-1, NKX2-1, have been associated with development of ILD and pulmonary fibrosis." (PMID 29085824, 2017).
respiratory failure (4 papers, 2017 to 2023). The significant impairment of gas exchange within the lungs resulting in hypoxia, hypercarbia, or both, to the extent that organ tissue perfusion is severely compromised. "Epitope mimicry analysis revealed that respiratory failure in population with some MHC polymorphisms was due to the high similarity between envelope and surface glycoproteins and two human proteins important for the prevention of alveolar collapse and respiratory failure, NKX2-1 and ABCA3 proteins." (PMID 36897962, 2023).
Bamforth-Lazarus syndrome (3 papers, 2014 to 2018). Bamforth-Lazarus syndrome is a very rare syndrome of congenital hypothyroidism characterized by thyroid dysgenesis (in most cases athyreosis), cleft palate and spiky hair, with or without choanal atresia, and bifid epiglottis. "It should be noted that we excluded NKX2-1 and FOXE-1 from our analysis, based upon the fact that the phenotype presenting in our cohort showed no signs of Bamforth-Lazarus syndrome or neurological findings." (PMID 30304112, 2018).
epilepsy (3 papers, 2013 to 2025). A brain disorder characterized by episodes of abnormally increased neuronal discharge resulting in transient episodes of sensory or motor neurological dysfunction, or psychic dysfunction. "We demonstrate the use of our algorithm to predict novel candidate genes for human atrial fibrillation (such as HRH2, ATP4A, ATP4B, and HOPX) and epilepsy (e.g., PAX6 and NKX2-1)." (PMID 23800157, 2013).
lymphoma (3 papers, 2013 to 2022). A malignant (clonal) proliferation of B- lymphocytes or T- lymphocytes which involves the lymph nodes, bone marrow and/or extranodal sites. "This interrelation suggests that enhancement of ectopic oncogene expression (e.g. NKX2-1 in DLBCL) may result in transdifferentiation of the lymphoma cells into benign non-hematopoietic cells, representing a novel concept for cancer therapy." (PMID 23637834, 2013).
mucinous tumors (3 papers, 2017 to 2021). "On the contrary, NKX2‐1 was decreased in mucinous tumors which was consistent with its inhibitory role in gastric differentiation." (PMID 33439550, 2021). "Only 20% of NKX2-1-positive tumors were diffusely positive (vs. 41% of mucinous tumors), and 35% of NKX2-1-positive tumors were negative for pERK (vs. 18% of mucinous tumors)." (PMID 33821796, 2021).
pituicytoma (3 papers, 2019 to 2021). An extremely rare, WHO grade I, circumscribed and slow-growing tumor that arises from the neurohypophysis or infundibulum and described in adults. "This is substantiated by the nuclear expression of thyroid transcription factor-1 (TTF-1, encoded by the NKX2-1 gene) which is a marker expressed in normal pituicytes, spindle cell oncocytomas, pituicytomas, and granular cell tumors of the sella." (PMID 34661724, 2021).